NF1 (neurofibromin 1)
Diseases named in the same sentence as NF1 in open-access papers (continued):
Sharing a sentence is not in itself a finding about the gene and the disease.
small intestinal tumors (2 papers, 2016 to 2025). "The clinical, pathologic and genetic features of NF1-GISTs differ from those of sporadic GISTs, including the development of multiple small intestinal tumors, an absence of KIT and PDGFRA mutations, and an indolent nature." (PMID 26511941, 2016).
somatotroph tumor (2 papers, 2022 to 2025). "Thus, in at least some patients with NF1 and GH excess, the pituitary gland could be characterized by somatotroph tumor or hyperplasia." (PMID 35456261, 2022).
synovial sarcoma (2 papers, 2021 to 2026). "The most common molecular alterations (excluding canonical SS18::SSX fusions in synovial sarcoma) involved ATM (18%), ARID1A (9%), CTNNB1 (9%), PALB2 (9%), and NF1 (9%), while 46% of profiled cases showed no detectable alterations." (PMID 41504936, 2026).
T-Cell Lymphoma (2 papers, 2012 to 2017). "The direct association between NF1 and T-cell lymphoma in most previously reported cases or between NF1 and DLBCL in this present case is unclear." (PMID 22236362, 2012). "When inoculated with a T-cell lymphoma in vivo, Nf1+/− mice survived longer than their WT littermates." (PMID 29354122, 2017). "To address this question, we inoculated Nf1+/− mice and their WT littermates with the RMA/S T cell lymphoma transfected with an empty vector or the murine cd1d1 cDNA." (PMID 29354122, 2017).
Takayasu arteritis (2 papers, 2014 to 2015). A rare inflammatory large-vessel vasculitis primarily affecting the aorta and its major branches, but also other large vessels, causing stenosis, occlusion, or aneurysm. "In both NF1 and Takayasu’s arteritis, the presence of ostial stenosis and long-segment disease predisposes to restenosis." (PMID 24678641, 2014).
thoracic tumors (2 papers, 2009 to 2023).
thyroid (2 papers, 2016 to 2021). "In recent years, several studies identified genes that cooperate with RAS mutations in the pathogenesis or progression of thyroid and other types of cancers, such as NF1, APC, PTEN, KEAP1, NF2 and others." (PMID 34065786, 2021). "SPOP, NF1, BRIP, CNOT1, KMT2C and STAG2 mutations previously identified in PTC might be involved in thyroid tumorigenesis in a type-nonspecific manner." (PMID 27626165, 2016).
tibial pseudoarthrosis (2 papers, 2023 to 2025). "Deletion of the NF1 gene can affect bone development, leading to bone deformities, and it has been well established that children with congenital tibial pseudoarthrosis are closely linked to the inactive state of the NF1 gene." (PMID 41430724, 2025). "LOH of NF1 has been identified in cells extracted from skeletal and nervous tissues in affected individuals, such as tibial pseudoarthrosis, dystrophic scoliosis, or plexiform neurofibroma samples." (PMID 40225171, 2023).
ulcerative colitis (2 papers, 2022 to 2025). An inflammatory bowel disease involving the mucosal surface of the large intestine and rectum. "Neurofibromatosis type 1 (NF1) is an autosomal dominant genetic disorder resulting from mutations in the NF1 gene, while ulcerative colitis (UC) is a chronic inflammatory disease of the intestines with an unclear etiology." (PMID 41346988, 2025).
uterine cancer (2 papers, 2022 to 2025). Primary or metastatic malignant neoplasm involving the uterine corpus and/or the cervix. "The patient with uterine cancer also had FLCN, MEN1 and NF1 PGVs, though none of these three PGVs are typically associated with the uterine carcinoma phenotype either." (PMID 41465149, 2025).
Wolf-Hirschhorn syndrome (2 papers, 2007 to 2017). Wolf-Hirschhorn syndrome (WHS) is a developmental disorder characterized by typical craniofacial features, prenatal and postnatal growth impairment, intellectual disability, severe delayed psychomotor development, seizures, and hypotonia. "A panel that includes 1p36 deletion, 22q11.2 deletion, Smith-Magenis, Potocki-Lupski, Miller-Dieker, NF1 microdeletion and Wolf-Hirschhorn syndromes was designed and tested." (PMID 28158220, 2017).
abdominal aortic aneurysm (1 paper, 2019). Enlargement and ballooning of the vessel that supplies arterial blood to the abdomen, pelvis and legs. "We describe the case of a 67-year-old female with NF1 who underwent endovascular aneurysm repair (EVAR) for an abdominal aortic aneurysm (AAA) rupture." (PMID 30673931, 2019).
achondroplasia (1 paper, 2025). Achondroplasia is the most common form of chondrodysplasia, characterized by rhizomelia, exaggerated lumbar lordosis, brachydactyly, and macrocephaly with frontal bossing and midface hypoplasia. "Achondroplasia and NF1 were selected as exemplar diseases due to their multisystem involvement and the need for coordination across multiple clinical specialties." (PMID 40608210, 2025). "These conditions are considered “relatively common” among rare diseases, with NF1 affecting approximately 1 in 3,000 individuals and Achondroplasia occurring in 1 in 25,000 live births." (PMID 40608210, 2025). "This scenario is not unique to NF1 and Achondroplasia but is common across many rare genetic diseases." (PMID 40608210, 2025).
adrenal cancer (1 paper, 2014). A carcinoma involving a adrenal gland. "This is the first reported case with DNA analysis, which demonstrated the loss of heterozygosity (LOH) at the NF1 locus in the adrenal cancer, supporting the hypothesis of an involvement of the NF1 gene in the pathogenesis of ACC." (PMID 25520849, 2014).
adrenal hyperplasia (1 paper, 2015). "Here we present the analysis of Nf1Prx1 mice, as well as a NF1 patient with macronodular adrenal hyperplasia, indicating that Nf1 is indeed implicated in control of adrenal cortex function." (PMID 25775093, 2015). "Thus, somatic loss of both NF1 alleles appears to underlie adrenal hyperplasia in the index patient." (PMID 25775093, 2015). "Comparison of normal control tissue- and adrenal hyperplasia- derived genomic DNA revealed loss of heterozygosity (LOH) of the wild type NF1 allele, showing that biallelic NF1 gene inactivation occurred in the hyperplastic adrenal gland." (PMID 25775093, 2015).
adrenocortical tumors (1 paper, 2022). "However, few reports of adrenocortical tumors associated with MEN2 or NF1 have been reported." (PMID 35660748, 2022).
Airway obstruction (1 paper, 2014). Obstruction of conducting airways of the lung. "Rapid tumor enlargement is more common in patients with NF1-associated MPNSTs, which could relate to the suddenness in which our NF1 patient in case 3 presented with airway obstruction." (PMID 25548703, 2014).
Alpha-thalassemia (1 paper, 2019). Alpha-thalassemia is an inherited hemoglobinopathy characterized by impaired synthesis of alpha-globin chains leading to a variable clinical picture depending on the number of affected alleles.
ampullary adenocarcinoma (1 paper, 2023). "We identified two novel germline frameshift mutations in the NF1 gene that contribute to the relationship among NF1, GIST, NETs, and ampullary adenocarcinoma." (PMID 37773168, 2023).
amyotrophic lateral sclerosis (1 paper, 2022). Amyotrophic lateral sclerosis (ALS) is a neurodegenerative disease characterized by progressive muscular paralysis reflecting degeneration of motor neurons in the primary motor cortex, corticospinal tracts, brainstem and spinal cord. "For example, many SOD1 mutations can cause amyotrophic lateral sclerosis (ALS), NF1 mutations can cause pediatric brain tumors, RB1 mutations can cause retinoblastoma, and ETV6 mutations can cause pediatric acute lymphoblastic leukemia." (PMID 36276986, 2022).
anxiety disorder (1 paper, 2025). A category of psychiatric disorders which are characterized by anxious feelings or fear often accompanied by physical symptoms associated with anxiety. "Other factors that could impact stress include but are not limited to, social support, access to care, non‐NF1‐related stressors, and personal characteristics such as NF1‐related anxiety disorder or other mental health concerns." (PMID 40361300, 2025).
Aortic Rupture (1 paper, 2022). The tearing or bursting of the wall along any portion of the AORTA, such as thoracic or abdominal. "There was one case of spontaneous ascending aortic rupture in a pregnant woman with NF-1 in our review." (PMID 35414028, 2022).
astrocytic tumor (1 paper, 2025). A glial tumor of the brain or spinal cord showing astrocytic differentiation. "Astrocytic tumors with NF1 mut/loss had a significantly higher T/N ratio on their FDG-PET images compared with those without these alterations." (PMID 40786409, 2025). "The findings of our retrospective small cohort study suggest that in astrocytic tumors, PTEN mut/loss, EGFR mut/amp, and CDKN2A/B HD are strong MET accumulation factors, and NF1 mut/loss is a strong FDG accumulation factor." (PMID 40786409, 2025).
Asymmetric septal hypertrophy (1 paper, 2024). Hypertrophic cardiomyopathy with an asymmetrical pattern of hypertrophy, with a predilection for the interventricular septum and myocyte disarray. "Most likely, fetal cardiomyopathy, asymmetric septal hypertrophy, and subsequent diagnosis of NF1 are not coincidental." (PMID 38654147, 2024).
atherosclerosis (1 paper, 2014). A disease characterized by the build-up of fatty material and calcium deposition in the arterial wall resulting in partial or complete occlusion of the arterial lumen. "We therefore speculate that atherosclerosis is less likely than NF1 to explain this previously unreported association of arterial abnormalities." (PMID 24499535, 2014).
au (1 paper, 2021). "Regardless of family history, all NF1 patients suffered from café-au-lait macules, and pNF might carry diverse NF1 mutations." (PMID 33850471, 2021).
autoimmune encephalitis (1 paper, 2025). Inflammation of the brain secondary to an immune response triggered by the body itself. "Our patient’s disease course underscores how the intersection of NF1-associated immune dysregulation and iatrogenic CNS exposure may create a permissive environment for autoimmune encephalitis." (PMID 41487805, 2025).
B-cell lymphoma (1 paper, 2023). "7q32 deletions cover IRF5, a known tumor suppressor in B-cell lymphoma, while individuals with NF1 loss are at increased risk for NHL." (PMID 37495858, 2023).
bacteremia (1 paper, 2024). "In particular, HLp-nF1 is nonviable heat-killed microorganism, which exhibits a low risk of sepsis or bacteremia associated with probiotics, particularly in critically ill or vulnerable patients and pediatric populations, demonstrating comparable effects to those of viable probiotics." (PMID 38623309, 2024).
behavioral disorders (1 paper, 2022). "The prevalence rates of comorbid diagnoses in neurodevelopmental and behavioral disorders differed between the DMD and NF1 group." (PMID 36215287, 2022).
benign skin tumors (1 paper, 2021). "Mutations of the NF1 gene are responsible for neurofibromatosis type 1 (Nf1), a genetic disease characterized by skin pigmentation and benign skin tumors, low-grade tumors of the central and peripheral nervous systems, and learning and attention deficits in some patients." (PMID 34195691, 2021).
benign tumors of the retina (1 paper, 2021). "Retinal astrocytoma are benign tumors of the retina that occur sporadic or as first signs of genetic syndromes such as TSC or NF1." (PMID 33919815, 2021).
biliary tract cancer (1 paper, 2022).
bone mineralization disorders (1 paper, 2022). "Second, NF1 mutations cause neurofibroma protein deficiency, bone mineralization disorders, and bone strength reduction, resulting in insufficient holding force for internal fixation." (PMID 36061378, 2022).
brain sarcoma (1 paper, 2023). A sarcoma arising from the brain.
brainstem tumors (1 paper, 2013). "In fact, it should be stressed that the brainstem tumors associated with NF1 are currently considered a subgroup with further separations into focal and diffuse tumors." (PMID 23399325, 2013). "On the contrary, in NF1 affected children, an isolated focal pontine tumor localization represents an exceptional finding and brainstem tumors show generally a very much better prognosis." (PMID 23399325, 2013).
carcinomas of the esophagus (1 paper, 2013). "The study revealed that patients with NF1 have a significantly high risk of developing carcinomas of the esophagus, stomach, colon, liver, lung, thyroid, breast and ovary." (PMID 24137429, 2013).
carotid body paraganglioma (1 paper, 2021). A benign or malignant extra-adrenal parasympathetic paraganglioma arising from paraganglia adjacent to or in the bifurcation of the common carotid artery. "Out of the 24 patients, 9 (37.5%) carried pathogenic variants (2 SDHB, 7 NF1) and in one patient a novel VHL variant, classified as VUS was detected (VHL: p.36_37insSGPEE) in a young patient presenting with carotid body paraganglioma." (PMID 34439371, 2021).
cerebral infarction (1 paper, 2026). An ischemic condition of the brain, producing a persistent focal neurological deficit in the area of distribution of the cerebral arteries. "These severe cardiac structural abnormalities, which ultimately led to cerebral infarction, may be specifically associated with this unique NF1 variant." (PMID 41515658, 2026). "Notably, to the best of our knowledge and following a systematic literature search conducted by our research team, no cases of NF1 complicated by severe cardiac structural abnormalities that ultimately lead to cerebral infarction have been reported to date." (PMID 41515658, 2026).
cervical (1 paper, 2024). "Previous reports have shown that 50% of MPNST cases are associated with NF1; however, this is the first case of cervical MPNST in which an association with NF1 was confirmed." (PMID 39497595, 2024).
Chagas disease (1 paper, 2017). A parasitic infection caused by Trypanosoma cruzi. "Thus, the child could have been very thin by constitution or was cachectic as result of the suggested NF1, Chagas disease, and lung infection." (PMID 28403237, 2017).
Chiari malformation (1 paper, 2022). A rare genetic brain malformation characterized by displacement of the brain stem and cerebellum through the foramen magnum. "Among our patients, one had NF‐1 and one had Chiari malformation." (PMID 35698273, 2022).
chronic leukemia (1 paper, 2022). A slowly progressing leukemia characterized by a clonal (malignant) proliferation of maturing and mature myeloid cells or mature lymphocytes. "The pediatric population with NF1 gene defects includes patients at risk for developing hematopoietic malignancies such as acute or chronic leukemias or different types of lymphomas." (PMID 35053664, 2022). "Several types of hematopoietic malignancies like acute and chronic leukemias, respectively lymphoblastic and myelomonocytic leukemias correlated with NF1 gene defects have been reported." (PMID 35053664, 2022).
chronic myelomonocytic leukaemia (1 paper, 1994). "Over the 17 year study period there were five cases of chronic myelomonocytic leukaemia (CMML) in patients with NF-1 (relative risk 221; 95% CI 71-514), 12 cases of acute lymphoblastic leukaemia (ALL) (relative risk 5.4; 95% CI 2.8-9.4) and five cases of NHL (relative risk 10.0; 95% CI 3.3-23.4)." (PMID 7947106, 1994).
Chuvash polycythemia (1 paper, 2025). Chuvash erythrocytosis is a rare, genetic, congenital secondary polycythemia disorder characterized by increased hemoglobin, hematocrit and erythropoietin serum levels and normal oxygen affinity, which usually manifests with headache, dizziness, dyspnea and/or plethora. "Other underlying genetic syndromes in patients with PPGL-GN included MEN 4, MEN 2A VHL, NF1, Pacak-Zhuang syndrome, Chuvash polycythemia, and mutations in genes encoding SDH subunits B, C, and D." (PMID 40071066, 2025).
clear cell renal cell carcinoma (1 paper, 2024). "More in keeping with its growth inhibitory role during development there is convincing evidence that GRB10 acts as a tumour suppressor in at least two cases, that of clear cell renal cell carcinoma and in tumours from a cancer-prone mouse model heterozygous for the Neurofibromatosis 1 (Nf1) gene." (PMID 39343875, 2024).
co-infection (1 paper, 2014). "The co-infection of shRNA-PKC α and β did not induce the cytosol release of cytochrome c in Nf1 proficient cells." (PMID 25301738, 2014).
cognitive decline (1 paper, 2023). "Given that oxidative stress responses can impair cognitive function, it is plausible to hypothesize that NF-1-induced oxidative stress could serve as another contributor to cognitive decline in affected patients." (PMID 37876519, 2023).
colon adenoma (1 paper, 2014). An adenoma that arises from the colon. "Importantly, cell senescence is not restricted to mouse models, but has also been reported in premalignant human colon adenomas, and human benign lesions caused by the BRAFV600E mutation, or NF1 inactivation." (PMID 24618719, 2014).
colorectal GISTs (1 paper, 2025). "Surprisingly, gastric GISTs comprised 11.0% of cases, there were no colorectal GISTs, and 5.1% of NF1-GISTs harbored a KIT or PDGFRA mutation." (PMID 40043354, 2025).
colorectal tumours (1 paper, 1995). "A number of known or putative tumour-suppressor genes including NF1, BRCA1, NME1, NME2 and prohibitin are present on the long arm of chromosome 17, and this region has not been extensively analysed in colorectal tumours." (PMID 7734302, 1995).
cone-rod dystrophy (1 paper, 2023). Inherited retinal dystrophies that belong to the group of pigmentary retinopathies. "This rare association was suggestive of a cone-rod dystrophy gene situated close to the NF1 gene on chromosome 17." (PMID 37686284, 2023). "Specifically, cone-rod dystrophy has been reported in association with NF1 in two case reports." (PMID 37686284, 2023).
congenital glaucoma (1 paper, 2015). "When an NF1 -associated congenital glaucoma is diagnosed, visual loss due to ambiyopia and/or oncothlipsis is common and should be aggressively treated." (PMID 26514695, 2015). "Lastly, we suggest that NF1-associated congenital glaucoma should be treated in a multiple disciplinary setting, as early as possible." (PMID 26514695, 2015).
corticotropinoma (1 paper, 2025). "By qPCR, NF1 was significantly overexpressed in the tumor when compared with another NF-PitNET, but not when compared with a corticotropinoma." (PMID 39968302, 2025).
craniosynostosis (1 paper, 2024). Craniosynostosis is defined as the premature fusion of one or more cranial sutures leading to secondary distortion of skull shape resulting in skull deformities with a variable presentation. "Although this is not a distinctive craniofacial bone alteration for NF1, some other cases of craniosynostosis in patients affected by NF1 have been reported in the literature." (PMID 38893021, 2024).